CCL2 (C-C motif chemokine ligand 2)
Diseases named in the same sentence as CCL2 in open-access papers (continued):
Sharing a sentence is not in itself a finding about the gene and the disease.
ovarian carcinoma (continued). "We noted that Olaparib significantly up-regulated CD47 and CCL2 expression in ovarian cancer cells in-vitro." (PMID 37468567, 2023). "Our previous study showed that recombinant CCL2 protein promoted ovarian cancer cell proliferation by activating the ERK pathway." (PMID 37445830, 2023). "Exogenous CCL2 and the overexpression of CCL2 promoted the proliferation, migration, and invasion of ovarian cancer cells, whereas CCL2 inhibition decreased the biological functions of ovarian cancer cells." (PMID 37445830, 2023). "Combined anti-CD47 therapy with olaparib also reduced cytokine secretion of IL6, IL18 and CCL2 from ovarian cancer cells." (PMID 37468567, 2023). "Studies showed that plasma CCL2 levels are elevated in patients with high-grade ovarian cancer compared with healthy volunteers." (PMID 37445830, 2023). "CCL2 significantly promoted the proliferation, migration, and invasion of ovarian cancer cells by targeting MAP3K19." (PMID 37445830, 2023). "In the present study, cell migration and invasion assays were performed to determine the metastatic ability of CCL2 in ovarian cancer." (PMID 37445830, 2023). "Intriguingly, we identified the chemotactic factors CCL2 and CCL5 in the CM of macrophages and found that they were associated with the adhesion of ovarian cancer cells to mesothelial cells." (PMID 36766725, 2023). "Here, we found that exogenous CCL2 and the overexpression of CCL2 promoted the proliferation and metastasis of ovarian cancer cells." (PMID 37445830, 2023). "The present study exhibited that recombinant CCL2 protein promoted ovarian cancer cell migration and invasion." (PMID 37445830, 2023). "The present study demonstrated that exogenous CCL2 and CCL2 overexpression promoted the biological functions of ovarian cancer cells, whereas CCL2 knockout inhibited ovarian cancer cell activity, migration, and invasion." (PMID 37445830, 2023). "Omental adipocytes increase adipokine secretion, such as Interleukin 8 (IL-8) and C-C motif chemokine ligand 2 (CCL2) to promote homing of ovarian cancer cells to the omentum." (PMID 37180125, 2023). "On the other hand, CCL2 knockdown via CRISPR/Cas9 inhibited ovarian cancer cell proliferation, migration, and invasion." (PMID 37445830, 2023). "On the other hand, another study found that CCL2 is up-regulated in MA-148 ovarian cancer cells when treated with paclitaxel and/or carboplatin." (PMID 36403055, 2022). "CCL2 from mesenchymal stromal cells act on ovarian cancer cells and induces IL-6 secretion for chemoresistance dependent on IL-6 and PYK2." (PMID 36403055, 2022). "Currently, our group found that both CCL2 and IL-1β promote the proliferation and metastasis of epithelial ovarian cancer cells." (PMID 36403055, 2022). "A study compared the levels of CCL2 in tumor tissue and adjacent healthy tissues from patients with breast, gastric, and ovarian cancer, and consistently observed an increased level of CCL2 in tumor samples." (PMID 33603130, 2022). "Binding to its cognate receptor CCR2, CCL2 expedited the migration and invasion of ovarian cancer cells and improved cisplatin resistance." (PMID 36403055, 2022). "Omental adipocytes expressed a high level of CCL2 in an experimental mouse model of ovarian cancer peritoneal metastasis." (PMID 36403055, 2022). "The enhanced metastasis and invasion of ovarian cancer cells can be eliminated by blocking CCL2/CCR2 signaling transduction with CCL2 neutralizing antibodies or a CCL2 gene knockout defect." (PMID 36403055, 2022). "included 37 patients with primary ovarian cancer to investigate the relationship between CCL2 expression in tumor specimens and patient response to chemotherapy and survival outcomes." (PMID 35702353, 2022). "Recently, our group purified human recombinant CCL2 proteins and showed that exogenous CCL2 improved ovarian cancer cell proliferation by stimulating the MAPK/ERK signaling pathway and regulating JUN, RELB, and NF-κB2 expression levels." (PMID 36403055, 2022).
ovarian carcinoma (continued). "In support of this finding, it was observed that CCL2 facilitates migration and metastasis in ovarian cancer by activating the PI3K–AKT–mTOR pathway and its downstream effectors, HIF-1α and VEGF-A." (PMID 35884700, 2022). "With respect to anti-CCL2 mAbs, in an ovarian cancer xenograft mouse model, the anti-human CCL2 IgG1 human mAb Carlumab was found to enhance the efficacy of chemotherapies paclitaxel and carboplatin." (PMID 35020853, 2022). "They enhance the invasion of epithelial ovarian cancer cells by generating CCL2 through the P38-MAPK pathway." (PMID 36403055, 2022). "A phase I trial of carlumab, a CCL2 monoclonal antibody, in solid tumor patients, included eight ovarian cancer patients, and 1/8 of patients had a stable disease at 10.5 months." (PMID 35565348, 2022). "For example, ovarian cancer cells are capable of recruiting macrophages via CC-chemokine ligand 2 (CCL2)/Monocyte chemoattractant protein-1 (MCP-1), yet also polarize macrophages to an M2 state." (PMID 35565348, 2022). "CCL2 promoted PYK2 phosphorylation in ovarian cancer cells via IL-6 secretion in a coculture system." (PMID 34386431, 2021). "In a mouse model of ovarian cancer, adipocyte-derived CCL2 activated the PI3K/Akt/mTOR pathway to promote the metastasis of cancerous cells, but this pathway can be blocked by metformin." (PMID 34445235, 2021). "A previous study had confirmed that high level of CCL2 participated in increased chemosensitivity and improved survival outcomes in ovarian cancer cell." (PMID 34251980, 2021). "In murine ovarian cancer experiments, inhibition of CCL2 increased the response to carboplatin-paclitaxel." (PMID 32012728, 2020). "MSCs protect ovarian carcinoma cells from chemotherapy by secreting CCL5 and CCL2, which induce the release of IL-6 by ovarian carcinoma cells." (PMID 32630699, 2020). "CCL2 was highly expressed on paclitaxel-resistant ovarian cancer cells and showed an antitumor effect in ovarian cancer." (PMID 32850861, 2020). "In a study investigating CCL2 gene expression using tumor specimens from 37 ovarian cancer patients, CCL2 mRNA expression was correlated with objective complete response, chemosensitivity, and progression-free survival." (PMID 33297571, 2020). "Ovarian cancer cells have been shown to express the canonical monocyte recruitment factors, CCL2 and CCL7." (PMID 33069212, 2020). "Preventing macrophage recruitment by pharmacological inhibition of chemoattractants, such as CCL2 (MCP-1), has proven successful in ovarian cancer, and pancreatic cancer." (PMID 31737559, 2019). "It is very plausible that this effect was associated with the higher secretion levels of several agents known to support ovarian cancer cell progression by these cells, such as CCL2, CXCL8, CXCL12, ICAM-1, IL-6, HGF, PAI-1, uPA, TGF-β1, and VEGF." (PMID 31086083, 2019). "The important role of CCL2 in TAM accumulation is supported by the evidences that the levels of tumor-derived CCL2 is correlated with the number of TAMs in several types of tumor, including pancreatic, breast and ovarian cancer." (PMID 31629410, 2019). "Another chemokine, CCL-2 was proven to be responsible for migration and adhesion of ovarian cancer cells." (PMID 30680411, 2019). "A CCL2 transcription in ovarian cancer cells is regulated by the NFκB, which is highly increased in high-grade ovarian cancers." (PMID 30680411, 2019). "A previous study showed that expression of CCL2 in ovarian cancer cells correlates with chemotherapy response and is reduced in cisplatin-resistant cells." (PMID 29518977, 2018). "A phase 2 clinical trial of trabectedin in ovarian cancer patients, showed a significant depletion of blood monocytes, as well as a reduction in CCL2 levels, in TAMs and ovarian tumor cells." (PMID 30274280, 2018).
ovarian carcinoma (continued). "Epithelial ovarian cancer cells release CCL2/MCP-1 to attract monocytes and convert them to TAMs, within the TME." (PMID 30274280, 2018). "They secrete IL-6, IL-8/CXCL8, CCL2, and adiponectin, which act on cancer cells via their respective receptors to support ovarian cancer cell metastasis." (PMID 28275576, 2017). "A pilot case–control study in Chinese population reported that the frequency of the heterozygote C/G at promoter of CCL2 was significantly less in ovarian cancer than in healthy controls." (PMID 27145753, 2016). "In ovarian cancer, CCL2 levels significantly correlated with histological grade and CCL2 was suggested as a differentiation marker between benign ovarian cysts and ovarian cancer." (PMID 26885690, 2016). "Recently, microarray analyses of tumors from ovarian cancer patients at greater biobehavioral risk (i.e., high depression and low social support) revealed an upregulation of MCP1 (reported as CCL2) gene expression." (PMID 25738355, 2015). "Although CCL2 has been originally thought to have an inhibitory effect on ovarian cancer progression, recent studies have indicated that CCL2 increases invasion of ovarian cancer cells and resistance to chemotherapy." (PMID 25790431, 2015). "Downregulation of MIF in ovarian cancer cells led to a decrease in the production of cytokines important in TAM recruitment such as CCL2 and CCL22 in vitro and an increase in survival and decrease in ascites in vivo." (PMID 24936477, 2014). "Ovarian cancer cells express factors that stimulate monocyte chemotaxis and maturation such as CCL2 and macrophage colony stimulating factor (M-CSF)." (PMID 24567915, 2014). "Following co-culture with ovarian cancer cells, macrophages develop a cell-surface phenotype similar to TAMs isolated from human ovarian tumors and a significant increase in genes such as CCL2, CCL22, TNFα, TGFβ1, and VEGF." (PMID 24936477, 2014). "It has been shown that the CCL2/CCR2 axis is a determinant of the degree of macrophage infiltration in ovarian cancer." (PMID 24384839, 2013). "Among chemokines, the CC subfamily, and particularly CCL2, is the most often expressed in ovarian cancer histotypes being particularly involved in macrophage recruitment." (PMID 20049170, 2010). "More recently, the analysis of ovarian cancer ascitic fluid and ascite cells allowed the identification of the expression of CCL2,-3,-4,-5,-8, and -22, altogether with their receptors (namely, CCR1, -2a,-2b, -3,-4,-5, and-8), at mRNA and protein level." (PMID 20049170, 2010). "In primary tumours, mRNA ISH showed expression of CCL2 in an average of 1.4% of cells in 23 out of 26 primary ovarian tumours, and ELISA detected CCL2 protein in ascites from ovarian cancer patients with a mean level of 4.28 ng ml−1." (PMID 15900302, 2005). "A previous study of CCL2 expression in seven ovarian cancer cell lines by RT–PCR and ELISA, found the highest levels in PEO14 and HL60, with lower levels in OVCAR3, PEO1 and PEO4 and barely detectable expression in SKOV3 and PEA2 cells." (PMID 15900302, 2005). "Using cDNA array screening of normal OSE cells and ovarian cancer cell lines, we previously identified CCL2 as a gene whose expression is downregulated or lost in ovarian cancer cell lines." (PMID 15900302, 2005). "CCL2 expression has also been found to be increased in paclitaxel resistant cell lines and in the serum of ovarian cancer patients following paclitaxel treatment." (PMID 15900302, 2005). "To investigate the mechanism of downregulation of expression of CCL2, we treated a panel of ovarian cancer cell lines with the methyltransferase inhibitor 5-azacytidine." (PMID 15900302, 2005). "In this study, we showed that EVs from ovarian cancer cells upregulated genes related to the inflammatory response, including immune cell–attracting cytokines (CCL2, CCL3/L1, CCL15, CCL18, and CCL20), interleukins (IL1B and IL32), and cell–cell adhesion transcripts (VCAM1 and ICAM1)." (PMID 40689422, 2025).
ovarian carcinoma (continued). "In conclusion, we identified CCL2 as a commonly expressed chemokine in patients with local and metastatic ovarian cancer and successfully demonstrate that armed CAR-T cells with enhanced homing to CCL2-expressing ovarian cancer are more efficacious due to improved peritoneal trafficking in vivo." (PMID 41424784, 2025). "CCL2 is also readily detected in the serum of patients with ovarian cancer." (PMID 41424784, 2025). "It has been found that serum level of CCL2 is increased in patients with ovarian cancer." (PMID 39003350, 2024). "Additionally, CCL2 knockout in A2780 cells inhibited the biological activity of ovarian cancer cells." (PMID 37445830, 2023). "Additionally, CCL2 inhibition by neutralizing antibodies reduced epithelial ovarian cancer cell invasion, indicating the crucial role of CCL2 in ovarian cancer development." (PMID 37445830, 2023). "Additionally, CCL2 expression is upregulated in MA-148 (an ovarian cancer cell line) under treatment with paclitaxel and/or carboplatin." (PMID 37445830, 2023). "CCL2 from mesenchymal stromal cells acts on ovarian cancer cells and induces IL-6 secretion." (PMID 37445830, 2023). "CCL2 stimulates ovarian cancer progression by enhancing angiogenesis." (PMID 37445830, 2023). "CCL2 overexpression promoted the proliferation, migration, and invasion of ovarian cancer cells." (PMID 37445830, 2023). "MAP3K19 was the key target for CCL2 in the regulation of ovarian cancer progression." (PMID 37445830, 2023). "CCL2 inhibition by neutralizing antibodies reduced epithelial ovarian cancer cell invasion." (PMID 37445830, 2023). "Additionally, CCL2 expression is upregulated in MA-148 (an ovarian cancer cell line) under treatment with paclitaxel and carboplatin." (PMID 37445830, 2023). "However, clinical data and animal experiments are required to understand the role of CCL2 in ovarian cancer development in detail." (PMID 37445830, 2023). "Moreover, CCL2 secreted by mesothelial cells has been suggested to promote peritoneal metastasis and adherence of ovarian cancer cells." (PMID 36766725, 2023). "MAP3K19 knockout inhibited the biological functions of ovarian cancer cells, and thus, it may be the critical target of CCL2 in the regulation of ovarian cancer development." (PMID 37445830, 2023). "The present study showed the correlation between CCL2 and ovarian cancer, suggesting that CCL2 may be a novel target for ovarian cancer therapy." (PMID 37445830, 2023). "Additionally, mitogen-activated protein three kinase 19 (MAP3K19) was the key target for CCL2 to regulate ovarian cancer progression." (PMID 37445830, 2023). "In addition, inhibition of CCL2 by neutralizing antibodies reduced the invasion of epithelial ovarian cancer cells." (PMID 36403055, 2022). "There is a correlation between CCL2 and IL-1β in the progression of ovarian cancer." (PMID 36403055, 2022). "Also, in vitro experiments illustrated that ovarian cancer cells with higher CCL2 expression were more sensitive to the traditional chemotherapeutic drugs paclitaxel and cisplatin." (PMID 35702353, 2022). "CCL2 has also been shown to play a role in the action of other cells on ovarian cancer cells." (PMID 36403055, 2022). "CCL2 also stimulates the progression of ovarian cancer by enhancing angiogenesis." (PMID 36403055, 2022). "These exosomes are more readily absorbed by omental macrophages, are able to drive the polarization of macrophages toward the M2 phenotype, and upregulate the expression of CXCL5 and CCL2 in macrophages, thereby boosting metastasis and omental colonization in ovarian cancer." (PMID 36477408, 2022). "CCL2 is also involved in the communication between other stromal cells and ovarian cancer cells." (PMID 36403055, 2022).
ovarian carcinoma (continued). "In a retrospective study including 86 ovarian cancer patients, 67 benign ovarian cysts, and 42 healthy women, ovarian cancer patients had significantly higher serum CCL2 levels, and serum CCL2 levels were statistically significantly correlated with histological malignancy." (PMID 33297571, 2020). "A CCL2 level is positively correlated with TAMs concentration in ovarian cancer tissues." (PMID 30680411, 2019). "Synthesis of tumor-promoting factors including CCL2 and IL-6 is minimized in TAMs and ovarian cancer cells upon treatment by Trabectedin (Yondelis), an agent that originates from the tunicate Ecteinascidia turbinate, binds DNA minor grooves and inhibits monocyte differentiation into macrophage." (PMID 28929459, 2018). "Additionally, adipocytes of the omentum contribute to a protumor TME by secreting IL-6, IL-8, CCL2, and adiponectin, which support ovarian-cancer cell metastasis." (PMID 30200478, 2018). "Nieman and colleagues identified that omental adipocytes secrete IL-6, IL-8, chemokine (C-C motif) ligand 2 (CCL2), and tissue inhibitor of metalloproteinases-1, and that mAbs to each of these factors inhibited chemotaxis of ovarian cancer cells toward adipocytes by at least 50%." (PMID 24567915, 2014). "The reduced levels of CCL2 found in ovarian cancers may be promoting tumour growth through various growth factors produced by monocytes attracted to the tumour, in addition to evading the destructive response of the host macrophages and T cells." (PMID 15900302, 2005). "To test whether the silencing of CCL2 expression in the ovarian cancer cell lines is related to hyper-methylation of CpG dinucleotides, we treated cell lines with 0, 0.5 or 2.0 μM of the methyltransferase inhibitor 5-azacytidine." (PMID 15900302, 2005). "This showed that expression of CCL2 is greatly reduced in ovarian cancer cell lines." (PMID 15900302, 2005). "We transfected the HEY and OVCAR8 ovarian cancer cell lines with CCL2 cloned into pcDNA3.1, but were unable to develop stable clones with comparable levels of expression to the HOSE cells, and so were unable or to interpret the consequences of in vitro or in vivo assays (data not shown)." (PMID 15900302, 2005). "This suggests that a selective advantage may result from downregulation of CCL2 expression, consistent with a role of CCL2 in the pathobiology of ovarian cancer." (PMID 15900302, 2005). "Furthermore, TAM production of CCL2 as a driver of additional macrophage recruitment has also been well documented, and elevated expression of CCL2 is inversely proportional to patient prognosis in breast and ovarian carcinomas." (PMID 38426622, 2024). "Ovarian cancer cells treated in vitro with CCL2/MCP-1 and carboplatin significantly increased spheroid formation ability and increased SOX2 expression, suggesting that CCL2/MCP-1 could be one of the secreted factors from macrophages during chemotherapy that supports CSC features." (PMID 39287565, 2024). "Thus, CCL2 knockout inhibited ovarian cancer proliferation, migration, and invasion." (PMID 37445830, 2023). "However, the effect of CCL2 on ovarian cancer progression is unclear." (PMID 37445830, 2023). "We hypothesized that CCL2 plays an important role in ovarian cancer progression." (PMID 37445830, 2023). "Thus, the present study uncovered the association between CCL2 and ovarian cancer, suggesting that CCL2 may be a promising therapeutic target in ovarian cancer." (PMID 37445830, 2023). "Thus, CCL2 is a vital molecular participant in ovarian cancer progression and may be a promising therapeutic target for ovarian cancer." (PMID 37445830, 2023).